RN7SKP12 (RN7SK pseudogene 12)
Gene: Miscellaneous RNA gene on chromosome 1 (242,188,647 to 242,188,789, reverse strand). Ensembl gene ENSG00000252084.
Homologues: Orthologues: chimpanzee 7SK (99% identical), mouse Gm54555 (58% identical), guinea pig 7SK (57% identical), zebrafish 7SK (43% identical). Paralogues in human: RN7SKP38 (71% identical), RN7SKP176 (70% identical), RN7SKP112 (69% identical), RN7SKP170 (69% identical), RN7SKP205 (69% identical), RN7SKP206 (69% identical), RN7SKP240 (69% identical), RN7SKP243 (69% identical), RN7SKP250 (69% identical), RN7SKP255 (69% identical), RN7SKP268 (69% identical), RN7SKP9 (69% identical), and 283 more.